WDR54 (WD repeat domain 54)
Description:
Plays a role in the adhesion and fusion of the sperm-oocyte membrane through its interactions with IZUMO1 and IZUMO1R/JUNO (By similarity). When cross-linked to form dimers and trimers, it has a regulatory effect on ERK signaling pathway activity in response to EGF stimulation. Colocalizes with the EGF receptor in WDR54-specific vesicle where it sustains the internalization and controls the degradation of the EGF receptor after EGF stimulation.
Synonyms: FLJ12953
Tractability: Antibody: UniProt places it where antibodies can reach, with medium confidence; its Gene Ontology location is reachable by antibodies, with medium confidence. PROTAC: UniProt records ubiquitination sites on it; ubiquitination databases record sites on it; its protein half-life has been measured.
Gene: Protein-coding gene on chromosome 2 (74,421,477 to 74,425,770, forward strand). Ensembl gene ENSG00000005448.
Subcellular location: Vesicle; Cytoplasm; Cell membrane
Subcellular location (Human Protein Atlas): Acrosome; Golgi apparatus; Vesicles; Centriolar satellite; Cytosol; Flagellar centriole; Mid piece; Nucleoli; Primary cilium tip; Principal piece
Gene Ontology:
Molecular function: protein binding; protein homodimerization activity
Biological process: negative regulation of receptor internalization; regulation of epidermal growth factor receptor signaling pathway; fusion of sperm to egg plasma membrane involved in single fertilization; single fertilization
Cellular component: vesicle; cytoplasm; motile cilium; plasma membrane
Genetic constraint (gnomAD): Loss-of-function variants: 44 observed, 46.28 expected, observed/expected ratio (o/e) 0.95, 90% interval 0.75 to 1.22. The upper end of that interval is the gene's LOEUF score, 1.22, which puts it in group 5 of 6, group 1 being the genes least tolerant of losing a copy. Missense variants: 409 observed, 452.82 expected, observed/expected ratio (o/e) 0.9, 90% interval 0.83 to 0.98. Synonymous variants: 169 observed, 180.02 expected, observed/expected ratio (o/e) 0.94, 90% interval 0.83 to 1.07.
Homologues: Orthologues: chimpanzee WDR54 (99% identical), macaque WDR54 (98% identical), pig WDR54 (92% identical), dog WDR54 (90% identical), mouse Wdr54 (89% identical), rat Wdr54 (88% identical), guinea pig WDR54 (87% identical), rabbit WDR54 (87% identical), zebrafish wdr54 (56% identical), tropical clawed frog wdr54 (53% identical), Caenorhabditis elegans sel-10 (13% identical). Paralogues in human: FBXW7 (16% identical), WDR49 (15% identical), FBXW11 (15% identical), BTRC (15% identical), WDR64 (15% identical), EFCAB8 (13% identical), TRAF7 (13% identical), WDR86 (13% identical), FBXW8 (12% identical), FBXW9 (11% identical), PAAF1 (9% identical), FBXW12 (8% identical), and 2 more.
Diseases named in the same sentence as WDR54 in open-access papers:
WDR54 is named in the same sentence as 5 diseases in open-access papers, as found by Europe PMC text mining. Sharing a sentence is not in itself a finding about the gene and the disease. The quoted sentences say what the papers report.
pan (1 paper, 2023). "In pan cancer, NXF2B, MSLNL, PCGF1, INO80B-WBP1, LBX2-AS1, MRPL53, LBX2, TTC31, WDR54 and WBP1 were co-altered in the TLX2-altered group." (PMID 37758722, 2023).
tumor (1 paper, 2025). "Combined with the rare variant findings, these findings are consistent with previous reports of increased expression of WDR54 and cell/tumor proliferation." (PMID 40631191, 2025).
WDR54 also shares sentences with these, for which no sentence is quoted: Anxiety (1 paper); cancer (1); coronary heart disease (1).